ZNF135 (zinc finger protein 135)
Description:
May be involved in transcriptional regulation (Probable). Required for regulation of cell morphology and cytoskeletal organization.
Synonyms: ZNF61; ZNF78L1; pHZ-17; pT3
Tractability: PROTAC: ubiquitination databases record sites on it.
Gene: Protein-coding gene on chromosome 19 (58,059,239 to 58,086,310, forward strand). Ensembl gene ENSG00000176293.
Subcellular location: Nucleus
Subcellular location (Human Protein Atlas): Cytosol
Pathways (Reactome):
Gene expression (Transcription): Generic Transcription Pathway
Gene Ontology:
Molecular function: protein binding; DNA-binding transcription factor activity, RNA polymerase II-specific; RNA polymerase II cis-regulatory region sequence-specific DNA binding
Biological process: regulation of transcription by RNA polymerase II; regulation of DNA-templated transcription
Cellular component: nucleus; cytoplasm
Genetic constraint (gnomAD): Loss-of-function variants: 11 observed, 11.87 expected, observed/expected ratio (o/e) 0.93, 90% interval 0.58 to 1.52. The upper end of that interval is the gene's LOEUF score, 1.52, which puts it in group 6 of 6, group 1 being the genes least tolerant of losing a copy. Missense variants: 719 observed, 842.39 expected, observed/expected ratio (o/e) 0.85, 90% interval 0.8 to 0.91. Synonymous variants: 314 observed, 323.44 expected, observed/expected ratio (o/e) 0.97, 90% interval 0.88 to 1.07.
Homologues: Orthologues: macaque ZNF135 (96% identical), chimpanzee ZNF135 (93% identical), dog ZNF135 (82% identical), pig ZNF135 (58% identical), rabbit ZNF135 (55% identical). Paralogues in human: ZNF470 (43% identical), ZNF658 (39% identical), ZNF585A (38% identical), ZNF33B (38% identical), ZNF585B (37% identical), ZNF197 (37% identical), ZFP28 (37% identical), ZNF546 (36% identical), ZNF471 (35% identical), ZNF484 (35% identical), ZNF568 (34% identical), ZNF41 (34% identical), and 164 more.
Diseases named in the same sentence as ZNF135 in open-access papers:
ZNF135 is named in the same sentence as 33 diseases in open-access papers, as found by Europe PMC text mining. Sharing a sentence is not in itself a finding about the gene and the disease. The quoted sentences say what the papers report.
schizophrenia (1 paper, 2025). A major psychotic disorder characterized by abnormalities in the perception or expression of reality. "We further linked this discrepancy to reduced levels of the repressor ZNF135 in schizophrenia, which derepressed motif-matched TNEs." (PMID 41276612, 2025).
cancer (6 papers, 2009 to 2024). A tumor composed of atypical neoplastic, often pleomorphic cells that invade other tissues. "Seven genes are hypermethylated in ten cancer sites: six encoding zinc finger transcription factors (ZNF135, ZNF354C, ZNF415, ZNF542, ZNF671, ZSCAN18) and one encoding a transmembrane protein (TMEM25)." (PMID 25631659, 2015). "Of note, the methylation levels of PTGDR and ZNF135 genes were substantially higher in cancers when compared to precancerous tissues." (PMID 37405952, 2023). "We further investigated the genes with the top 3 inactive core promoters: ZNF154, ZNF135, ZNF667-AS1 and ZNF667, using public data from commonly used cancer databases." (PMID 38084904, 2024). "We leveraged public data from diverse popular cancer projects and found a decrease in the expression of putative housekeeping tumor suppressor genes (ZNF154, ZNF135, ZNF667, and ZNF667-AS1) due to aberrant methylation of their core promoters in several cancer subtypes." (PMID 38084904, 2024). "Finally, for the set of putative housekeeping tumor suppressor genes (ZNF135, ZNF154, ZNF667 and ZNF667-AS1), e.g. genes whose HK-CPs are active in less than 20% of the cancer cells, we performed a comprehensive analysis using cancer samples of 17 projects from TCGA." (PMID 38084904, 2024).
ZNF135 also shares sentences with these, for which no sentence is quoted: tumor (4 papers); breast carcinoma (2); infection (2); myopathy (2); Alzheimer disease (1); asthma (1); Ataxia (1); Atrophy (1); Autoimmunity (1); bone cancer (1); cardiomyopathy (1); chronic myelogenous leukemia (1); colon cancer (1); combined immunodeficiency (1); diabetes (1); Genital ulcers (1); glioma (1); hearing loss (1); hypertrophic cardiomyopathy (1); metastatic melanoma (1); microcephaly (1); mucopolysaccharidosis VII (1); Nystagmus (1); Oculomotor apraxia (1); pneumonia (1); sarcoidosis (1); Sepsis (1); septic shock (1); stomach cancer (1); viral encephalitis (1).
A further 1 disease shares a sentence with ZNF135 in 1 paper.